IL17A (interleukin 17A)
Diseases named in the same sentence as IL17A in open-access papers (continued):
Sharing a sentence is not in itself a finding about the gene and the disease.
migraine (14 papers, 2020 to 2025). "The study also revealed that higher levels of IL-12p70 and IL-17A are associated with an increased risk of pediatric migraine, highlighting their potential as predictive markers for the condition." (PMID 40149800, 2025). "Nonetheless, our data open promising avenues for future research, including the role of IL-17A and associated immune pathways, as well as the potential impact of modulating specific microRNAs, such as miR-101 or miR-143, on migraine frequency and severity." (PMID 41010614, 2025). "This increase in BBB permeability facilitated the entry of IL-17A from the periphery into the CNS, triggering neuroinflammation and sensitizing the trigeminal system, a hallmark of migraine pathophysiology." (PMID 40331982, 2025). "The authors suggest that IL-17A (together with IL-12) may have diagnostic/predictive value in childhood migraine." (PMID 41010614, 2025). "Elevated serum levels of IL-12p70 and IL-17A may increase the risk of migraine in children, which has certain diagnostic and predictive value." (PMID 38356891, 2024). "Moreover, elevated serum IL-12p70 and IL-17A levels will also increase the risk of migraine in children, which has certain predictive value for migraine diagnosis." (PMID 38356891, 2024). "Our preliminary findings suggest a potential role for peripheral inflammatory markers, including specific microRNAs (miR-197, miR-101, and miR-143) and cytokines (TNF-α, IL-6, and IL-17A), in the pathophysiology of migraine." (PMID 41010614, 2025). "These preclinical results strongly suggest that IL-17A is an active mediator in the pathophysiology of migraine." (PMID 41010614, 2025). "Studies in murine models of induced chronic migraine have shown that high levels of IL-17A in the blood can infiltrate the trigeminal nucleus and trigger central neuroinflammation, activating nociceptive pathways of migraine." (PMID 41010614, 2025). "A recent study found that cytokine levels, including IL-4, TNF-α, IL-17A, and IL-12p70, are elevated in children with migraine." (PMID 40149800, 2025). "In conclusion, serum levels of IL-4, TNF-α, IL-17A, and IL-12p70 are increased in children with migraine." (PMID 38356891, 2024). "Based on the current clinical application of 12 types of cytokine detection methods including IL-12P70 and IL-17A, this study mainly explored the cytokines related to the presence of migraine in children and their levels." (PMID 38356891, 2024). "The results suggested that an increase in serum IL-17A level had a significant effect on migraine (OR = 1.066, 95%CI 1.016–1.119, p = 0.010)." (PMID 38356891, 2024). "An increase in serum IL-12p70 (OR = 1.267, 95%CI 1.054–1.523, p = 0.012) and IL-17A (OR = 1.066, 95%CI 1.016–1.119, p = 0.010) levels had a significant effect on migraine." (PMID 38356891, 2024). "In fact, a study in children found IL-17A and IL-12p70 higher in migraine vs. controls and varying with attack frequency, hinting that Th17 pathways might be involved in more frequent attacks." (PMID 41377228, 2025). "Elevated levels of miR-197, miR-101, and miR-143, along with proinflammatory cytokines (TNF-α, IL-6, and IL-17A), align with the hypothesis of migraine as an inflammatory process." (PMID 41010614, 2025). "Our findings present intriguing research perspectives, such as understanding the involvement of IL-17A and related pathways or examining whether the modulation of microRNAs, such as miR-101 or miR-143, influences the frequency and intensity of migraine." (PMID 41010614, 2025). "When serum IL-17A level was >7.99 pg/mL (0–20.60 pg/mL), the sensitivity and specificity in migraine diagnosis were 88.6 and 60.6% respectively, and when serum IL-17A level was >20.60 pg/mL, the sensitivity and specificity were only 25.35 and 93.18%, respectively." (PMID 38356891, 2024). "This process was a novel mechanism in NTG-induced chronic migraine, suggesting that IL-17A might be a novel target in the treatment of migraine." (PMID 34979902, 2022).
migraine (continued). "Interestingly, the inhibition of neuroinflammation using ibuprofen effectively mitigated IL-17A-induced sensitization, suggesting that an IL-17A blockade may be a promising therapeutic target for migraine prevention." (PMID 40331982, 2025). "Additionally, IL-17A is a promising target involved in migraine and rats with NTG-induced migraine might serve as a useful neuroinflammatory tool to investigate the interventions for migraine, including an anti-IL-17A strategy and protection of the BBB." (PMID 34979902, 2022). "Moreover, several findings suggested a sharp increase in plasma T‐helper 17 (Th17) cells, a member of three subsets of CD4+ T cells, and effector cytokines levels including IL‐4, IL‐5, IL‐6, IL‐10, and IL‐17A during neurovascular inflammation among migraine patients." (PMID 32892507, 2020). "The prediction model suggested that the increase in serum IL-17A and IL-12p70 levels had a certain predictive value for the diagnosis of migraine, which was not completely consistent with reports in previous studies." (PMID 38356891, 2024). "Collectively, NTG mediates the increase in BBB permeability around the MO to transfer IL-17A through the induction of the lipid transport function, neuroinflammation, and TNC activation, which is a novel mechanism of NTG-induced migraine that possibly bypasses the trigeminovascular system." (PMID 34979902, 2022). "However, when the MAPK pathway is activated, it can lead to the production of several proinflammatory cytokines, potentially including IL-17A, although this specific link is not directly established in the context of migraine." (PMID 41010614, 2025).
myasthenia gravis (14 papers, 2015 to 2026). Myasthenia gravis (MG) is a rare, clinically heterogeneous, autoimmune disorder of the neuromuscular junction characterized by fatigable weakness of voluntary muscles. "The primary endpoints are quantitative myasthenia gravis (QMG) test; measurement of the amount of Treg cells and cytokines such as interferon-γ (IFN-γ), interleukin-4 (IL-4), interleukin-17A (IL-17A), and transforming growth factor-β (TGF-β); and corticosteroid or immunosuppressive agent dosage." (PMID 33371107, 2020).
pancreatic ductal adenocarcinoma (14 papers, 2019 to 2025). An infiltrating adenocarcinoma that arises from the epithelial cells of the pancreas. "Increased circulating Th17 cells and serum IL-17A were found to be involved in the development and metastasis of pancreatic ductal carcinoma (PDAC) in a clinical trial." (PMID 39906741, 2024). "FOXP3+RORγt+ Tregs were increased in PBMC from patients with pancreatic ductal adenocarcinoma, and they produced IL-17A and expressed high level of LAG3." (PMID 31354747, 2019). "In this study, we examined whether IL-17A/IL-17RA promotes pancreatic ductal adenocarcinoma (PDAC) aggressiveness in terms of survival and cancer stem cell modulation." (PMID 32210079, 2020).
polyp (14 papers, 2009 to 2025). A usually exophytic mass attached to the underlying tissue by a broad base or a thin stalk. "HIF-1α expression in SM of patients with CRSwNP is significantly increased compared to SM of healthy controls and the HIF-1α level in polyp tissues is positively associated with IL-17A production and neutrophilic inflammation." (PMID 36292050, 2022). "The increased act1 production was shown to be significantly associated with IL-17A levels in polyp tissues, providing a clue that the IL-17A/act1 axis may play a crucial role in MUC5AC production in NP patients." (PMID 24892823, 2014). "To determine the optimal DSS concentration for an ETBF-induced polyp formation model within this framework, we compared the effects of 1% and 2% DSS on polyp development, survival rate, and circulating levels of IL-17A, CXCL1, and nitric oxide." (PMID 40650003, 2025). "Signature Th1 (IFN-γ), Th2 (IL-5 and IL-13), and Th17 (IL-17A) cytokines were measured in iNKT cells from four inflammatory subtypes of polyp tissues." (PMID 35720287, 2022). "Expressions of IFN-γ, IL-5, IL-17A, IL-25 and IL-10 were significantly higher in the 3 months and 6 months murine polyp model than in the control mice." (PMID 27584662, 2016). "The percentage of IFN-γ+ cells amongst the IL-21+CD8+ T cells was significantly higher than the percentage of IL-17A+ and IL-4+ cells in the polyp tissues (P < 0.001)." (PMID 27468819, 2016). "Here we analyzed the IL-17 family cytokines IL-17A, E and F and their receptors IL-17RA, RB and RC in bladder tissues from patients with cystitis, polyp and bladder cancer." (PMID 27716046, 2016). "Increased IL-17A has been proposed as being responsible for enhanced tissue neutrophilia, collagen deposition and corticosteroid resistance in polyp tissues." (PMID 26594227, 2015). "By using DNA microarray analysis, we identified 46 upregulated related genes, including MUC5AC (6.25 fold) and act1 (4 fold), in nasal epithelial cells, confirming the association of IL-17A, MUC5AC and act1 in polyp tissues." (PMID 24892823, 2014). "By setting the median of IL-17A+ cells in polyp tissues as the cutoff value (6.7/HPFs), we subdivided them into two subgroups: IL-17Ahigh (n = 12) and IL-17low (n = 13)." (PMID 24892823, 2014). "Increased IL-17A has been proposed to be responsible for enhanced tissue neutrophilia, collagen deposition and corticosteroid resistance in polyp tissues." (PMID 24892823, 2014). "Nasal polyp fibroblasts were cultured alone or with IL-17A (10 ng/mL) and TNF-α (10 ng/mL), alone and in combination." (PMID 23283206, 2009). "Moreover, there was significant difference in act1 mRNA in polyp tissues (1.1[0.7, 1.8]) and normal controls (0.8[0.3, 1.2])(p<0.05), and act1 mRNA was significantly correlated with IL-17A mRNA in polyp tissues (p<0.05)." (PMID 24892823, 2014). "There was significant association of IL-17A and MUC5AC mRNA in polyp tissues (p<0.05)." (PMID 24892823, 2014). "In this study, we established a close relationship between excessive MUC5AC expression, goblet cell hyperplasia and IL-17A production in polyp tissues, providing the clue that Th17 cells may play an important role in the excessive MUC5AC production and goblet cell hyperplasia." (PMID 24892823, 2014). "Thus, hypoxia may be involved in polyp pathogenesis through regulation of IL-17A secretion." (PMID 29254228, 2017). "We next examined the gene expression levels of IL-17A, MUC5AC and act1 in polyp tissues and normal controls." (PMID 24892823, 2014). "We enrolled 25 NP patients and 22 normal controls and examined the expression of IL-17A, MUC5AC and act1 in polyp tissues by immunohistochemical (IHC) staining, quantitative polymerase chain reaction (qPCR) and western blot." (PMID 24892823, 2014). "In accordance with the histological staining, the mRNA levels of IL-17A and MUC5AC were significantly increased in polyp tissues compared with the normal controls (p<0.05)." (PMID 24892823, 2014).
polyp (continued). "We found that increased IL-17A production was significantly correlated with MUC5AC and act1 expression and goblet cell hyperplasia in polyp tissues (p<0.05)." (PMID 24892823, 2014). "Both IL-17A and MUC5AC immunostaining were significantly increased in polyp tissues compared with the normal controls (p<0.05)." (PMID 24892823, 2014). "The mean number of IL-17A+ cells per HPF was 6.7[2.9, 11.8] in polyp tissues and 1.6[0.8, 2.4] in normal controls; the mean staining score of MUC5AC was 2.2[1.7, 3.0] in polyp tissues and 0.6[0.4, 1.1] in normal controls." (PMID 24892823, 2014). "Due to the absence or low expression of IL-17A in polyp tissues in western patients, Th17 cells have not been well documented in the pathogenesis of CRSwNP." (PMID 26594227, 2015). "Due to the absence or low expression of IL-17A in polyp tissues in western patients, Th17 cells have not been well documented in the pathogenesis of NP." (PMID 24892823, 2014). "The mRNA level of IL-17A was 3.3[2.0, 5.5] in polyp tissues and 0.8[0.4, 1.2] in normal controls, and the mRNA level of MUC5AC was 4.4[2.3, 6.3] in polyp tissues and 1.2[0.4, 2.2] in normal controls." (PMID 24892823, 2014).
relapsing-remitting multiple sclerosis (14 papers, 2014 to 2025). The most common clinical variant of multiple sclerosis, characterized by recurrent acute exacerbations of neurologic dysfunction followed by partial or complete recovery. "IL-17A levels in CSF have been reported to be associated with breakdown of the BBB in animal models of relapsing-remitting multiple sclerosis." (PMID 36312009, 2022). "Overexpressed IRF4 in naive CD4+ T cells derived from relapsing remitting multiple sclerosis patients significantly increased their ability to secrete IL-17A, IL-17F, IL-21, and IL-22." (PMID 28808358, 2017). "For instance, we have recently evidenced that CD28-mediated upregulation of pro-inflammatory cytokines (i.e., IL-8, IL-6, IL-21, and IL-17A) was higher in human primary T lymphocytes from relapsing-remitting multiple sclerosis patients (RRMS) compared with HD." (PMID 28491063, 2017). "In addition, we analyzed clinical and radiological features (n = 201), levels of serum IFN-γ and IL-17A (n = 86), complete remission ratio by IFN-β (n = 38) in all of relapsing-remitting multiple sclerosis (RRMS) patients enrolled in this study." (PMID 32169103, 2020).
silicosis (14 papers, 2012 to 2025). Silicosis is a respiratory disease caused by breathing in (inhaling) silica dust. "Lastly, IL-17A-producing cells, such as γδ T cells and T helper 17 (Th17) cells, have been implicated in driving silicosis." (PMID 40119408, 2025). "Therefore, we performed this meta-analysis to precisely evaluate the association between the IL-1α +4845G/T, IL-1β +3953C/T, IL-1RA +2018T/C, IL-1β -511C/T, IL-6 -634C/G, IL-6 -174G/C, and IL-17A -832A/G polymorphisms and silicosis susceptibility." (PMID 40182855, 2025). "It has been reported that the IL-17F +7488 G-allele was correlated with the increased risk of accelerated silicosis, compared to IL-17A +832 in the Tunisian population, which might be ascribed to the variance of genotype frequency and the function of IL-17 in different ethnicities." (PMID 40182855, 2025). "Silica induces silicosis and leads to abnormally elevated levels of interleukin-17A (IL-17A) in lung tissue." (PMID 39796197, 2025). "They found that in experimental silicosis the acute alveolitis induced by silica is IL‐17A dependent, but this cytokine appears dispensable for the development of the late fibrotic lung responses to silica." (PMID 30378252, 2019). "Instillation of silica particles apparently activated the differentiation of Th17 cells and the secretion of IL-17A at the early stage of silicosis." (PMID 27069316, 2016). "Patients with silicosis seem to have a chronic inflammatory process that is consistent with the augmented levels of some pro-inflammatory cytokines, i.e., IL-1β, IL-6, IL-7, IL-8, IL-16, IL-17A, IL-33 and TNF-α were observed in this work." (PMID 36675056, 2023). "Additionally, PFD enhances lung function in silicosis models by inhibiting IL-17A secretion, suggesting IL-17A may be a key therapeutic target." (PMID 40470053, 2025). "Since PFD reduced the severity of silicosis by inhibiting the epithelial mesenchymal transition (EMT), regulating the TGF-β 1/Smad2/3 signaling pathway, and inhibiting the production of IL-17A, we used it as a positive control in our study." (PMID 35401236, 2022).
ulcers (14 papers, 2015 to 2025). "Similarly, increased levels of IL-17A and IL-8 were observed in the gastric mucosa of gastric ulcer and non-ulcer H. pylori-infected patients compared to uninfected non-ulcer patients, and both IL-17A and IL-8 are strongly correlated with an increase in neutrophil infiltration in infected patients." (PMID 32041355, 2020).
alveolitis (13 papers, 2010 to 2025). "The eight-time exposure of ASD alone (14-week study) deteriorated bronchitis and alveolitis, which accompanied with further increase of cytokines IL-1β, IL-6, IL-12, IL-17A and TNF-α; and chemokines KC, MIP-1α, and RANTES in BALF." (PMID 23731974, 2013). "In hypersensitivity pneumonitis, the effects of IL-17A were dependent on signaling in the structural cells, but not in the bone marrow-derived cells." (PMID 26367130, 2015). "However, we show here that lung inflammation induced by Saccharopolyspora rectivirgula (SR) induced Hypersensitivity pneumonitis (SR-HP) results in a neutrophil independent, and ITK independent Th17 responses, although ITK signals are required for γδ T cell production of IL17A." (PMID 35210549, 2022).
chronic lung disease (13 papers, 2014 to 2025). According to the definitions of the American and British Thoracic Societies, including pulmonary functional tests, X-rays, and CT scans for items such as fibrosis, bronchiectasis, bullae, emphysema, nodular or lymphomatous abnormalities. "The IL-17A/IL-17RA axis has been reported to participate in several acute and chronic lung diseases." (PMID 36411467, 2022). "We investigated the effects of IL-17A plus TNF-α, 2 cytokines with relevant roles in CF and other chronic lung diseases." (PMID 36219481, 2022). "The observed disparate clinical outcomes in chronic lung diseases by sex support the investigation of the impact of gonadotrophic hormones on STAT3 signaling, specifically in the context of the profibrotic cytokines, IL-17A and TGF-β1." (PMID 36899902, 2023).
demyelinating disease (13 papers, 2014 to 2025). A broad group of disorders that affect the myelin sheaths that cover the neurons. "At present, different studies have shown varied views on the relationship between IL-17A and demyelinating diseases." (PMID 35296090, 2022). "We hope to shed new light on the functions of IL-17A in brain inflammatory injury, to highlight the need for further revealing the pathogenesis of the demyelinating disease, allowing for optimization of existing treatment plans and proposing new treatment methods." (PMID 35296090, 2022).
disc degeneration (13 papers, 2017 to 2026). "A review of IL-17A literature demonstrated a reliable relationship with various forms of pain, including inflammatory, neuropathic, and chronic pain, as well as disc degeneration." (PMID 40649738, 2025). "We evaluated the protein levels of IL‐6, the mRNA of which was obviously elevated by IL‐17A treatment, and COX‐2, which is one of the major components of disc degeneration and which causes pain." (PMID 30207057, 2018). "Additionally, IL‐17A may lead to an increase in COX‐2 expression via the activation of MAPK pathways in disc degeneration." (PMID 30207057, 2018). "Therefore, IL‐17A may offer a potential target for therapeutic intervention for disc degeneration." (PMID 30207057, 2018).